EFEMP1 (EGF-like fibulin extracellular matrix protein 1)
Diseases named in the same sentence as EFEMP1 in open-access papers (continued):
Sharing a sentence is not in itself a finding about the gene and the disease.
prostate carcinoma (10 papers, 2011 to 2024). A carcinoma that arises from epithelial cells of the prostate gland. "They revealed that both histone deacetylation and promoter methylation contribute to the downregulation of EFEMP1 that was significantly observed in prostate cancer in comparison with other urologic malignancies as well as normal prostatic tissues." (PMID 35473807, 2022). "High EFEMP1 expression inhibits the progression of prostate cancer by suppressing cell proliferation and migration and promoting cell apoptosis." (PMID 34204134, 2021). "Some of these are lung, liver, breast, and prostate cancers, where EFEMP1 promoter methylation and/or expression were down-regulated." (PMID 21955618, 2011). "Finally, EFEMP1 acts as a tumor suppressor in prostate carcinoma, while most members of the fibulin family are crucial to tumorigenesis." (PMID 39201614, 2024).
Retinal dystrophy (10 papers, 2016 to 2025). Retinal dystrophy is an abnormality of the retina associated with a hereditary process. "An SSCP analysis study identified a potential disease-causing exon shift in EFEMP1, the gene encoding EFEMP1, in patients with both Doyne Honeycomb and Malaria Leventinese Retinal Dystrophy." (PMID 36830640, 2023). "Mutation EFEMP1 have been associated with the development of drusen deposits and retinal neovascularization, two primary characteristics identified in both Doyne Honeycomb Retinal Dystrophy and Malaria Leventinese." (PMID 36830640, 2023). "Even though there is no direct link between EFEMP1 and AMD pathogenesis, this interaction between HTRA1 and EFEMP1 yet again points towards a common disease mechanism possibly shared between different retinal dystrophies." (PMID 36936905, 2023).
glaucoma (9 papers, 2011 to 2025). Increased pressure in the eyeball due to obstruction of the outflow of aqueous humor. "EFEMP1 variants are implicated by association in primary open angle glaucoma (POAG), an ophthalmic pathology with a relatively more complex aetiological genetic component compared to ML/DHRD." (PMID 32911658, 2020). "Insight into the potential mechanistic underpinning of these GWAS EFEMP1–glaucoma associations may be gleaned from the studies’ concomitant gene and tissue enrichment analyses." (PMID 32911658, 2020). "Another notable common finding across the literature is that loci associated with the EFEMP1-related glaucoma endophenotypes (IOP, VCDR, OCA) are relatively enriched in cell or tissue types that can be broadly classified as either musculoskeletal or connective tissue-related." (PMID 32911658, 2020). "A total of 11 unique protein-coding genes posterior probability (PP) of H4 > 0.70 finally remained, including GSTM3 for senile cataract, WARS1, C3, IGFBP7, and PILRA for AMD, ECI1, LCT, and NPTXR for glaucoma, EFEMP1 for myopia, and SIRPG and SIGLEC14 for DR." (PMID 39408566, 2024). "The most notable example is EFEMP1, a well-known candidate gene for glaucoma and other eye pathologies." (PMID 32393163, 2020). "To date, more than 15 loci have been identified for glaucoma, and the causative gene has been identified for 5 of these loci: GLC1A (MYOC/TIGR), GLC1E (OPTN), GLC1F (ASB10), GLC1G (WDR36), and GLC1H (EFEMP1)." (PMID 28150229, 2018).
nasopharyngeal carcinoma (9 papers, 2011 to 2020). A carcinoma arising from the nasopharyngeal epithelium. "EFEMP1 is downregulated in nasopharyngeal carcinomas, and its loss-of-function significantly correlates with advanced tumor and lymph node metastasis stages by increasing the activity of phospho-AKT." (PMID 25987128, 2015). "And in nasopharyngeal carcinoma, EFEMP1 suppressed cell migration and invasion via the PI3K/AKT pathway." (PMID 27351229, 2016). "Reduced EFEMP1 expression and/or EFEMP1 promoter methylation occurs in lung, liver, breast, colon, prostate, and nasopharyngeal carcinoma." (PMID 27713911, 2016). "EFEMP1 has been reported in the study of exosome of nasopharyngeal carcinoma." (PMID 32280689, 2020). "EFEMP1 expression in GBM, hepatocellular and nasopharyngeal carcinoma is correlated with a favorable prognosis." (PMID 27713911, 2016).
age-related macular degeneration (8 papers, 2013 to 2025). Age-related loss of vision in the central portion of the retina (macula), secondary to retinal degeneration. "Recently, EFEMP1 has been demonstrated to be a potential biomarker for choroidal neovascularization in age-related macular degeneration, and for choroidal thickness change in myopia." (PMID 38984127, 2024). "EFEMP1 gene expression data in ocular tissues of patients with age-related macular degeneration (AMD) and healthy controls from GSE29801." (PMID 33584252, 2020).
hepatocellular carcinoma (8 papers, 2013 to 2022). A malignant tumor that arises from hepatocytes. "EFEMP1 promoter methylation was also suggested as an underlying mechanism for the low expression of fibulin-3 in hepatocellular carcinoma (HCC)." (PMID 35473807, 2022). "Decreased expression of EFEMP1 (epidermal growth factor-containing fibulin-like extracellular matrix protein) in hepatocellular cancer cells is a predictor of tumour spread and metastasis, and consequently worse prognosis." (PMID 35173190, 2022). "The relationship between EFEMP1 and the development of hepatocellular carcinoma (HCC) and the molecular mechanism are not fully understood." (PMID 30972979, 2019).
lymph node metastasis (8 papers, 2013 to 2024). "The EFEMP1 gene encoding fibulin-3, a member of the extracellular matrix glycoprotein family associated with lymph node metastasis, vascular invasion and poor prognosis, was also found to be hypermethylated and downregulated in MLPS compared to normal fat." (PMID 38254762, 2024). "High expression of EFEMP1 was significantly associated with high pathological stage, high histological grade, poor prognosis and lymph node metastasis of BLCA." (PMID 37123010, 2023). "In cervical cancer, upregulation of EFEMP1 not only promoted angiogenesis but also associated with lymph node metastasis." (PMID 27015552, 2016). "In our previous study, we noted that EFEMP1 was downregulated in EC and was associated with lymph node metastasis." (PMID 27015552, 2016). "In our study, immunohistochemical data showed the low expression of EFEMP1 was associated with lymph node metastasis, and that cell function assays indicated the ability of EFEMP1 to dampen both the metastases and potential invasiveness of the primary tumor." (PMID 23840707, 2013). "High EFEMP1 immunoexpression was significantly associated with high primary pathologic T (p < 0.001), lymph node metastasis (p = 0.001), high histological grade (p < 0.001), vascular invasion (p < 0.001), perineural invasion (p = 0.021) and high mitosis (p < 0.001)." (PMID 34204134, 2021). "High EFEMP1 immunoexpression significantly correlated with high pathologic stage, high histological grade, lymph node metastasis, vascular invasion, perineural invasion and high mitosis (all p < 0.05)." (PMID 34204134, 2021). "Immunohistochemistry revealed that patients with lymph node metastasis displayed weaker EFEMP1 expression." (PMID 23840707, 2013). "Expression of EFEMP1 was significantly decreased in patients showing lymph node metastasis (P = 0.014)." (PMID 23840707, 2013).
malignant mesothelioma (8 papers, 2015 to 2022). A malignant neoplasm of the pleura or peritoneum, arising from mesothelial cells. "Soluble mesothelin-related peptide (SMRP), osteopontin or EFEMP1 (Fibulin-3) are well described biomarkers for malignant mesothelioma with moderate sensitivity and specificity." (PMID 27713145, 2016).
Hernia (7 papers, 2018 to 2024). "Rs3791675 at EFEMP1, a gene involved in connective tissue homeostasis, also associates with hernias and carpal tunnel syndrome." (PMID 32184442, 2020). "The third, rs3791675 at the EFEMP1 locus, associates with conditions related to aberrant connective tissue function (hernias and carpal tunnel syndrome)." (PMID 32184442, 2020). "In our analyses, the locus containing EFEMP1 showed association with all five forms of hernia." (PMID 35680855, 2022). "The strongest association was observed at 2p16.1 (EFEMP1), closely followed by 1q41 (ZC3H11B) and 11p13 (WT1) which were all identified as shared susceptibility loci on analysis of the individual hernia cohorts." (PMID 36584111, 2022). "To our knowledge, this study also represents the first GWAS of hiatus hernia in which we identified eight susceptibility loci of which four loci (2p16.1 (EFEMP1), 6p22.2 (BTN2A1), 7q33 (CALD1), 11p13 (WT1) are known to correlate with abdominal hernia." (PMID 36584111, 2022). "Five biologically relevant loci were discovered on individual hernia analyses to confer shared susceptibility to multiple hernia phenotypes including 1q41 (ZC3H11B), 2p16.1 (EFEMP1), 6p22.1 (MHC region), 7q33 (CALD1) and 11p13 (WT1)." (PMID 36584111, 2022). "It is noteworthy that 47% of the FKBP14-kEDS patients described developed inguinal or umbilical hernias, a phenotype that is also observed in Efemp1-knockout mice." (PMID 31288483, 2019).
macular dystrophies (7 papers, 2012 to 2025). "Mutations of EFEMP1 can lead to macular dystrophy, and the expression of EFEMP1 was high in human and macaque foveal MGs." (PMID 34691611, 2021). "Mutations in EFEMP1 result in macular dystrophy with subretinal deposits." (PMID 22876139, 2012). "ML/DHRD is a rare macular dystrophy that is caused by a p.R345W mutation in the ECM protein, epidermal growth factor-containing fibulin-like extracellular matrix protein 1 (EFEMP1), also known as fibulin-3 (FBLN3 or F3)." (PMID 41198612, 2025). "We searched the electronic patient records of our large inherited retinal disease cohort, quantifying numbers of males and females with the more common (non-ABCA4) inherited macular dystrophies (associated with BEST1, EFEMP1, PROM1, PRPH2, RP1L1, and TIMP3)." (PMID 38700873, 2024). "Significant sex imbalances have been observed in certain autosomally-inherited macular dystrophies (such as those associated with ABCA4, BEST1 and EFEMP1), although the underlying mechanisms remain unclear." (PMID 39632990, 2025).
melanoma (6 papers, 2019 to 2025). A malignant, usually aggressive tumor composed of atypical, neoplastic melanocytes. "The AMPK activator Metformin also displays anti-cancer activity, particularly in cases of melanoma in which cancer cell growth is inhibited through direct effects on miR-192-5p-EFEMP1 and miR-584-3p-SCAMP3 pathways." (PMID 33493138, 2021). "The growth of melanoma tumors is inhibited following EFEMP1 and SCAMP3 silencing by miR-192-5p and miR-584-3p targeting, respectively." (PMID 33493138, 2021). "We demonstrated that miR-192-5p and miR-584-3p played crucial roles in the regulation of melanoma cell growth or invasion ability through the targeting of EFEMP1 and SCAMP3, respectively." (PMID 30754729, 2019). "In our study, we observed that metformin significantly suppressed melanoma cell motility by modulating the miR-192-5p/EFEMP1 axis." (PMID 30754729, 2019). "EFEMP1 and SCAMP3 knockdown significantly suppressed melanoma cell growth, but only EFEMP1 knockdown inhibited its motility abilities." (PMID 30754729, 2019). "It significantly suppresses melanoma cell motility by modulating the miR‐192‐5p/EFEMP1 axis." (PMID 41085102, 2025). "In conclusion, our study demonstrated that metformin treatment suppressed melanoma cell growth and invasion ability, which might be accomplished partially through the modulation of both miR-192-5p/EFEMP1 and miR-584-3p/SCAMP3 axes." (PMID 30754729, 2019). "Our findings indicated that miR-192-5p and miR-584-3p might contribute to metformin-induced growth and motility suppression in melanoma cells through silencing their target genes EFEMP1 and SCAMP3." (PMID 30754729, 2019). "In our study, we also found that miR-192 was up-regulated in melanoma cell lines after metformin treatment and that miR-192 could suppress melanoma cell growth and invasion through directly silencing EFEMP1 expression." (PMID 30754729, 2019). "Knockdown of EFEMP1 could reduce melanoma cell growth and invasiveness and promote apoptosis." (PMID 41085102, 2025). "After transfection of si-EFEMP1 and si-SCAMP3 into melanoma cells, the expression levels of individual genes were confirmed through Western blotting and real-time PCR." (PMID 30754729, 2019). "In conclusion, the results suggested that metformin treatment suppressed the motility and growth of melanoma cells due to direct modulation of miR-192-5p-EFEMP1 and miR-584-3p-SCAMP3 axes in melanoma cells." (PMID 31534778, 2019). "Furthermore, metformin also decreases cell growth and invasion of melanoma through modulation of miR-192-5p/EFEMP1 and miR-584 3p/SCAMP3 axes in a wide range of melanoma cell lines." (PMID 37370809, 2023). "The results indicated that metformin treatment suppressed the motility and growth of melanoma cells because it might directly modulate miR-192-5p-EFEMP1 and miR-584-3p-SCAMP3 axes in melanoma cells." (PMID 30754729, 2019). "They used siRNA to investigate the effects of EFEMP1 and SCAMP3 knockdown on melanoma cell growth." (PMID 31534778, 2019).
biliary atresia (5 papers, 2018 to 2025). A rare, biliary tract disease characterized by progressive obliterative cholangiopathy of the intra- and extrahepatic bile ducts, occurring in the embryonic/ perinatal period, leading to severe and persistent neonatal jaundice and acholic stool. "Genome-wide association studies (GWASs) have identified a genetic associated between EFEMP1 and biliary atresia (BA)." (PMID 36114336, 2022). "In addition, a genome-wide association study has linked EFEMP1 to biliary atresia, a fibrotic disease of the extrahepatic biliary tract in newborns." (PMID 40243889, 2025). "Other studies have demonstrated that mutations in FOXA2, GPC1, ADD3, PKD1L1, EFEMP1/3, STIP1, XPNPEP1, REV1 and JAG1 genes can increase an individual’s genetic susceptibility to biliary atresia." (PMID 37324459, 2023). "Other genes including FOXA2, GPC1, ADD3, PKD1L, EFEMP1/3, STIP1 were found to be associated with biliary atresia." (PMID 37324459, 2023).
osteoarthritis (5 papers, 2015 to 2024). A noninflammatory degenerative joint disease occurring chiefly in older persons, characterized by degeneration of the articular cartilage, hypertrophy of bone at the margins and changes in the synovial membrane. "Compared with age-matched healthy subjects, median levels of the serum EFEMP1 proteins Fib3-1 and Fib3-2 were elevated in patients with osteoarthritis (OA)." (PMID 25987128, 2015). "The zebrafish has been used to study the impact of Efemp1 (EGF-containing fibulin extracellular matrix protein 1, a protein of the extracellular matrix that is upregulated in the blood, urine, and bones of osteoarthritic patients) in osteoarthritis." (PMID 39791729, 2024).
Stroke (5 papers, 2016 to 2025). Sudden impairment of blood flow to a part of the brain due to occlusion or rupture of an artery to the brain. "Other single nucleotide polymorphisms including rs7214628 in TRIM65 and rs78857879 in EFEMP1 had also been verified at genome-wide significance level by one later genome-wide meta-analysis study in overall combined community populations with stroke patients of European ancestry." (PMID 31396257, 2019).
breast tumor (4 papers, 2010 to 2018). "Recently another member of the Fibulin gene family, FBLN3 (EFEMP1) was shown to be frequently methylated in breast tumours." (PMID 20205715, 2010). "In a second gene expression data set of 7 breast tumor and 15 normal stroma samples (GSE8977), we observed the same differential expression for EFEMP1 and MMP1." (PMID 27468688, 2016).
dementia (4 papers, 2024 to 2025). Loss of intellectual abilities interfering with an individual's social and occupational functions. "Our results align with previous human cohort studies reporting an association between EFEMP1 and brain aging and dementia, suggesting that EFEMP1 may play a more widespread role in the aging process across diverse organs." (PMID 40606020, 2025). "Furthermore, plasma EFEMP1 has beenalso associated with brain aging and dementia." (PMID 38809962, 2024).
gastric cancer (4 papers, 2015 to 2025). A primary or metastatic malignant neoplasm involving the stomach. "Given its potential to inhibit tumor growth and invasion in different cancers, EFEMP1 - targeted therapies may have clinical potential in future gastric cancer treatment." (PMID 41367615, 2025). "While EFEMP1 (HR = 1.94, 95% CI 1.27–2.97, p < 0.001), ANKRD29 (HR = 1.77, 95% CI 1.28–2.44, p < 0.001), and STOX2 (HR = 1.50, 95% CI 1.08–2.07, p = 0.014) are all associated with a positive prognostic value for gastric cancer patients." (PMID 41367615, 2025). "Among 20 shared core genes across disease stages, 13 genes (e.g., FCRL3,EFEMP1,ANKRD29,STOX2) were identified as unfavorable prognostic factors for gastric cancer." (PMID 41367615, 2025). "qPCR analysis revealed that the significant expressions of SPARC, EFEMP1, RGS5 and SERPINE1 were significantly upregulated in gastric cancer tissues compared to the normal tissues." (PMID 41584584, 2025). "The key genes included in the LASSO-Cox regression model (including SPARC, EFEMP1, RGS5 and SERPINE1) were significantly upregulated in gastric cancer compared to the normal tissue." (PMID 41584584, 2025). "FCRL3, EFEMP1, ANKRD29, and STOX2 may serve as potential biomarkers for monitoring the transition from precancerous lesions to gastric cancer, offering insights into the mechanisms of gastric carcinogenesis and supporting early diagnosis and intervention strategies." (PMID 41367615, 2025).
heart failure (4 papers, 2020 to 2023). Inability of the heart to pump blood at an adequate rate to meet tissue metabolic requirements. "An elevated EFEMP1 has previously been demonstrated to be associated with a greater odds of heart failure, CVD mortality, and all-cause mortality, suggesting that it may have roles in the development or progression of cardiac and lung diseases." (PMID 35390066, 2022). "While the association of GDF-15 with lung fibrosis, heart failure, and PAH has previously been established, our results demonstrate a novel association of EFEMP1 with new onset of restrictive lung physiology." (PMID 35390066, 2022). "Together, this data supports Efemp1 RNA-seq analysis, and demonstrates that fibulin-3 is upregulated in the plasma of acute heart failure, is correlated with established measures of severity of disease, and is upregulated in the left ventricle of end-stage human heart failure patients." (PMID 37696945, 2023). "Our networks succinctly illustrate the most influential nodes in both types of heart failure; for example, in ICM myocardium, a cluster of ECM proteins such as EFEMP1, LUM, and COL6A2 are highly influential, as is TF in the coagulation cascade." (PMID 32487995, 2020). "Fibulin-3 protein expression was two-fold higher in left ventricular tissue of heart failure patients, relative to non-failing (p = 0.009); in line with Efemp1 RNA-seq analysis." (PMID 37696945, 2023).
Hepatic fibrosis (4 papers, 2018 to 2024). The presence of excessive fibrous connective tissue in the liver. "In view of these points, it is possible that Fibulin-3 secreted by EFEMP1-expressing cells may play some role in liver fibrosis in MASLD." (PMID 38829196, 2024). "Our liver cell type-specific expression analysis of Efemp1 in normal rats showed it was highly expressed in portal fibroblasts compared with other liver cell populations, which also supports a possible role in hepatic fibrosis." (PMID 30102696, 2018). "EFEMP1 and FBLN5 are ECM proteins and highly express in portal fibroblasts, they have been proved to play a role in progressive liver fibrosis." (PMID 33971821, 2021).